HK2 (hexokinase 2)
Diseases named in the same sentence as HK2 in open-access papers (continued):
Sharing a sentence is not in itself a finding about the gene and the disease.
cancer (881 papers, 2002 to 2026). A tumor composed of atypical neoplastic, often pleomorphic cells that invade other tissues. "HK2, which encodes a rate‐limiting enzyme in glycolysis, is responsible for dysregulated glycolysis in cancers." (PMID 39993964, 2025). "This is consistent with the established biology wherein HK1 is the predominant isoform responsible for pathological stress responses in differentiated tissues, while HK2 is more frequently associated with proliferative states such as cancer." (PMID 41503885, 2025). "This decrease is particularly significant, as HK2 is a rate-limiting enzyme in glycolysis, and its upregulation is often associated with aggressive cancers." (PMID 39859445, 2025). "High levels of HK2 expression have been reported in many different types of cancer, and this upregulation is typically associated with poor outcomes in patients." (PMID 40956859, 2025). "HK2 encodes the hexokinase 2 protein, is involved in the metabolism of glucose, and has also been reported to promote the proliferation of certain cancer cells." (PMID 38338965, 2024). "Hexokinase 2 (HK2), the primary enzyme that controls the speed of glycolysis, is closely linked to the growth and progression of cancer." (PMID 39834829, 2024). "Numerous studies have consistently reported that the abnormal overexpression of HK2 is closely associated with cancer development, metastasis, and resistance to chemotherapy and radiotherapy." (PMID 38383348, 2024). "HK2 (Hexokinase 2) catalyzes the first step of glycolysis and its upregulation in tumors is linked to enhanced glycolytic metabolism typical of cancer cells, suggesting its involvement in the Warburg effect and as a target for metabolic therapy." (PMID 38962012, 2024). "High expression of HK2 has been observed in various types of human cancers and is associated with unfavorable prognosis in patients with cancer." (PMID 38383348, 2024). "Intact PSA and hK2 are present at low concentrations in the bloodstream in healthy individuals and changes in these patterns are associated with aggressive types of cancer." (PMID 38407310, 2024). "High HK2 expression has been linked to a variety kind of cancer and is associated with poor overall survival in cancer patients." (PMID 39192292, 2024). "HK2 has been linked to malignant growth in many types of cancer, where it plays a key role in aerobic glycolysis." (PMID 37978561, 2023). "High expression of HK2 has been shown associated with poor clinical prognosis in patients with cancer." (PMID 37019900, 2023). "Mitochondria-bound HK2 is associated with enhanced tumorigenesis in cancer, which makes this specific mitochondria-bound isoform a more attractive target." (PMID 37529037, 2023). "The AKT pathway is implicated in regulating nuclear accumulation of HK2, thereby augmenting its association with mitochondria and enhancing glucose uptake in cancer cells." (PMID 38034101, 2023). "HK2 catalyzes the first step of glycolysis and it has been found upregulated in several types of cancer; its activity has been associated with the Warburg effect, e.g., high lactate production in the presence of oxygen." (PMID 36831133, 2023). "Hexokinase-2 (HK2) is overexpressed in cancer and has been associated with relapses and poor outcomes in solid tumors." (PMID 35159363, 2022). "Do these Hk2 mutations promote or impede cancer progression, given that they presumably impair glucose phosphorylation just as ScHxk2G238V does?" (PMID 35235554, 2022). "HK2 encodes Hexokinase 2 catalyzing the rate-limiting step of glucose metabolism and is therefore an enzyme that is highly expressed in rapidly growing cancer cells." (PMID 35922756, 2022). "Hexokinase 2 (HK2) is an enzyme that catalyses the conversion of glucose to glucose-6-phosphate, which has been found to be associated with malignant tumour growth." (PMID 35982398, 2022).
cancer (continued). "Overall, the elevated expression of HK2 causes significantly more efficient glycolysis in malignant tumors than in normal cells, which promotes the proliferation of cancer cells." (PMID 36230492, 2022). "Recently, it has been discovered that high HK2 expression is associated with a poor prognosis and endpoint of cancer in several tumors, indicating that HK2 is a possible therapeutic target for cancer." (PMID 36339566, 2022). "Given that cancer is generally associated with increased HsHk2 activity, we were surprised to discover that the COSMIC database reports three ScHxk2G238V-equivalent mutations in HK2 (A236S, A236T, and A684V) that are associated with various carcinomas." (PMID 35235554, 2022). "HK2 is an attractive drug target against human cancers 16, 35, 36, which has prompted a number of investigations into the underlying molecular basis of HK2 regulation in cancers." (PMID 33867844, 2021). "Hexokinase 2 was associated with elevated glycolytic flux, which was a characteristic of cancer cells." (PMID 33931981, 2021). "HK2 is highly expressed in a wide range of human cancers and is associated with poor outcomes of patients with diverse cancers." (PMID 34174908, 2021). "Overexpression of HK2 has been associated with as much as 70% of cancers and is a known participant in the Warburg Effect." (PMID 34748597, 2021). "Knockdown of HK2 causes a substantial decrease in glycolysis, and decreased proliferation in cancer cells, suggesting that targeting HK2 is a potential strategy for cancer therapy." (PMID 35006438, 2021). "Previous studies have confirmed that the expression of HK2 is significantly upregulated in many cancers and its high expression in cancers is associated with poor prognosis." (PMID 31918722, 2020). "It plays a role in the progression of cancer via its association with hexokinase 1 (HK1) and hexokinase 2 (HK2) in aerobic glycolytic cancers." (PMID 32327997, 2020). "The phosphoinositide 3-kinase (PI3K)/AKT pathway is hyperactivated in cancer cells, and it upregulates HK2 activity by increasing mitochondrial HK association." (PMID 33081387, 2020). "Hexokinase 2 (HK2) is a cancer-associated isoenzyme that catalyzes the first rate-limiting step of glucose metabolism, and depletion of HK2 in PC cell lines decreased lactate production, invasion, and metastasis." (PMID 33520999, 2020). "HK2 expression status has been reported to be associated with cancer cell aggressiveness including enhancing invasion, metastasis and therapeutic resistance." (PMID 31959767, 2020). "Hexokinase 2, a key glycolytic enzyme that phosphorylates glucose into G6P, has been reported to be upregulated in diverse cancers and strongly linked to chemoresistance." (PMID 32766131, 2020). "As a rate‐determining enzyme, HK2 catalyses the first essential step of glycolysis and is characterized as a metabolic hallmark of human carcinoma cells." (PMID 32885590, 2020). "The HectH9/HK2 pathway regulates cancer stem cell (CSC) expansion and CSC-associated chemoresistance." (PMID 31201299, 2019). "HK2 expression was significantly associated with advanced stage and high-grade cancers, and was an independent prognostic factor." (PMID 31212816, 2019). "HK2 is an attractive drug target against treatment-naïve and -resistant human cancers, sparking various investigations into the underlying molecular basis of HK2 regulation in cancer cells." (PMID 31201299, 2019).
cancer (continued). "In the current study, we identified that HectH9-promoted HK2 mitochondrial localization is an underlying cause of cancer cells’ resistance to 2-DG and that ablating HectH9 expression synergistically augmented cancer cell sensitivity to 2-DG." (PMID 31201299, 2019). "This VDAC1/HK2 association entails multiple advantages to cancer cells: a) blocks pro-apoptotic signals; b) fuels glycolysis with a continuous flux of mitochondrial ATP; and c) reduces sensitivity to feedback inhibition by HK2 product, glucose-6-phosphate." (PMID 30400835, 2018). "We found that CNAs in core glycolysis enzymes (e.g., HK2) and other cancer‐linked metabolic enzymes such as TIGAR are coordinately enriched in tumors with distinct CNA signatures." (PMID 28202506, 2017). "These include an enhanced rate of aerobic glycolysis (‘Warburg effect’) which in cancer cells is often linked to an increased expression of the rate-limiting glycolytic enzyme Hexokinase 2 (HK2)." (PMID 29290953, 2017). "It is widely accepted that overexpression of HK2 in cancer cells is associated with chemotherapy tolerance and apoptosis resistance." (PMID 28427230, 2017). "Many studies have reported a high level of HK2 expression in cancer cells, and this has been associated with the risk of metastasis and poor prognosis." (PMID 27926482, 2017). "Intriguingly, recent studies indicate that the HPV E6/E7 oncogenes cause the metabolic reprogramming in HPV-positive cancer cells by directly upregulating HK2 expression." (PMID 29290953, 2017). "High level of HK2 expression is associated with poor overall survival and prognosis in many types of cancers." (PMID 29285270, 2017). "In contrast, a high level of HK2 expression has been observed in many types of cancer, and expression is associated with poor overall survival in cancer patients." (PMID 27926482, 2017). "BrPA can react with the sulfhydryl group of cysteine residues, to cause the HK2 dislocation from the mitochondria in cancer cells." (PMID 28186160, 2017). "Among these, only the high level of HK2 expression has wildly been observed in cancer cells and is associated with poor overall survival in cancer patients." (PMID 26884725, 2016). "HK2 has a critical role in cancer progression, and its overexpression is associated with poor prognosis in many cancer types." (PMID 27588472, 2016). "The 75 remaining studies for the association of HK2 overexpression with cancer prognosis were evaluated by reading the full text." (PMID 27824926, 2016). "Mitochondria-bound HK2 has been shown to be associated with apoptosis and the escape from mitochondrial cell death in several types of cancer." (PMID 25938543, 2015). "The mechanisms underlying the shift from the Krebs cycle to glycolysis in cancer cells are well studied, and it is believed that hexokinase 2 (HK2) contributes to this process." (PMID 25938543, 2015). "Impaired expression of HK2, coding for hexokinase 2, in cancer-associated fibroblasts (CAF) resulted in a G1 phase cell cycle arrest." (PMID 26017754, 2015). "It has been suggested that the main cause of the Warburg effect in cancer cells is the abnormal upregulation of key enzymes, including HK2, the most important enzyme involved in the first step of glycolysis." (PMID 23251295, 2013). "Hexokinase catalyzes the first step of glycolysis; the hexokinase 2 isoform is directly associated with mitochondria and is overexpressed in many types of cancer." (PMID 21931642, 2011). "Additionally, inhibition of Met using a MET inhibitor (PHA-665752) has been found to decrease the expression of glycolysis initiation-associated hexokinase 2 (HK2) and promote the reactivation of oxidative phosphorylation in cancer cells within a NSCLC model." (PMID 39201787, 2024). "HK2 was also discovered to regulate lactate production and was also linked with cancer metastasis." (PMID 37110218, 2023).
cancer (continued). "And Hexokinase 2 (HK2) is involved in glucose metabolism in normal tissues, while in cancer cells, increased activity of HK2 is associated with cancer survival and growth, even if its expression levels are lower than in normal tissues, representing the role of metabolic reprogramming in tumors." (PMID 38099288, 2023). "The expression of HK2 is associated with advanced stage and high-grade cancers." (PMID 37110218, 2023). "This causes dissociation of HK2 from the mitochondria, which promotes apoptosis in cancer cells." (PMID 37259304, 2023). "However, HK2 expression sharply increases after normal cells are converted to cancer cells, which is considered a hallmark of many malignant tumors." (PMID 37580808, 2023). "Mitochondrial metabolism-related enzymes, such as SUMO-deficient hexokinase 2, bound to mitochondria, could reduce mitochondrial respiration and result in cancer cell proliferation." (PMID 36675580, 2023). "Additionally, we explored the association between genetic alteration of HK2 and the survival prognosis of different types of cancers." (PMID 36335239, 2022). "Therefore, HK2 expression is considered a hallmark of cancer cells that determines their high glycolytic flux." (PMID 35173161, 2022). "Moreover, the high expression of HK2 has also been associated with drug resistance and metastasis in various cancers, thus making HK2 a potential anticancer therapeutic target." (PMID 35265223, 2022). "Notably, HK2 expression was increased in 11 cancer types and was associated with overall survival in seven cancers, including HCC." (PMID 35603967, 2022). "Moreover, HK2 has been considered as a key cancer biomarker, which is associated with an advanced state of tumors and is related to poor prognosis of patients." (PMID 35006438, 2021). "HK2 induces chemoresistance by binding to the outer mitochondrial membrane or interacting with other cancer-associated factors, which can be a new target for cancer therapy." (PMID 34540667, 2021). "HK2 is highly expressed in cancers of the stomach, ovary, and cervix, and is associated with elevated glycolytic flux, which is a characteristic of cancer cells." (PMID 32806533, 2020). "Hexokinase 2 (HK2) is a member of the hexokinases (HK) that has been reported to be a key regulator during glucose metabolism linked to malignant growth in many types of cancers." (PMID 33324557, 2020). "HK2 is a cancer-associated isoenzyme catalyzing the first rate-limiting step of glucose metabolism." (PMID 31201299, 2019). "Furthermore, in cancer cells, HK2 associates with the voltage-dependent anion channel (VDAC1), located on the outer mitochondrial membrane, to protect malignant cells from mitochondrial membrane permeabilization." (PMID 31803611, 2019). "Therefore, we examined the subcellular localization of hexokinase 2 (HK2) whose expression is elevated in most cancer cells and which requires association with mitochondria for full activity and efficient ATP synthesis by mitochondria." (PMID 31558701, 2019). "Notably, high HK2 expression was associated with cancer metastasis and poor patient clinical outcomes." (PMID 31212816, 2019). "Our finding that T cells are able to withstand the loss of HK2 indicates that HK2 may be a promising candidate for cancer therapy." (PMID 30140438, 2018). "In conclusion, our meta-analysis provides evidence that HK2 may be a potential marker to predict the risk of all-caused mortality and cancer progression in patients with solid tumors of digestive system." (PMID 28415659, 2017). "Given that FOXM1, GLUT1 and HK2 play instrumental roles in cell proliferation and aerobic glycolysis of cancer cells, we sought to determine the underlying mechanisms that may be responsible for coexpression of these three biomarkers." (PMID 27351131, 2016).
cancer (continued). "In conclusion, our meta-analysis suggested that HK2 could act as an independent prognostic factor for patients with solid tumor, but the association between HK2 and prognosis varies according to cancer type." (PMID 27824926, 2016). "Differential interactions of HK1 and HK2 with mitochondria may underlie different glycolytic profiles in cancer cells." (PMID 24648844, 2014). "We speculate that loss of miR-143 in cancer cells might promote the metabolic shift towards aerobic glycolysis due to up-regulation of HK2." (PMID 22691140, 2012). "We hypothesize that loss of miR-143-mediated repression of HK2 can promote glucose metabolism in cancer cells, contributing to the shift towards aerobic glycolysis observed in many tumors." (PMID 22691140, 2012). "An association between HK2 expression, cancer stage, and survival found in the current study might therefore suggest that abnormal glycolysis is a feature of biologically aggressive tumors in HCC." (PMID 23071593, 2012). "Indeed, a recent meta-analysis provides evidence that HK2 could be a marker to predict the risk of all-cause mortality and cancer progression in patients with tumors of the digestive system." (PMID 32195170, 2020). "HK2 loci could have slight pathogenic potential especially at the post-reproductive age, which also coincides with the higher incidence of autoimmunity and cancer." (PMID 23938753, 2013). "Given its prominent role in glucose metabolism, it is critical we understand the regulation of HK2 to appreciate its role in normal physiological function as well as in disease states like cancers." (PMID 42193901, 2026). "Herein, we proposed multifunctional copper-based nano-PROTACs (CHNDs) to degrade hexokinase 2 (HK-2) and amplify cuproptosis for cancer therapy via dual mitochondrial energy depletion." (PMID 41924308, 2026). "HK2 also regulates stemness properties of cancer cells by upregulating key stemness genes such as NANOG, SRY-Box 9 (SOX9), CD117, octamer-binding transcription factor 4 (OCT4), and Krüppel-like factor 4 (KLF4)." (PMID 40427188, 2025). "Targeting HK2 exhibits high potential in cancer therapies; therefore, further investigation is required." (PMID 40076506, 2025). "Research on osteosarcoma therapies targeting L-arginine, lactate, and HK2 primarily aims to inhibit cancer cell metabolism and enhance immune responses." (PMID 40109854, 2025). "The inhibition of HK2 has been shown to effectively disrupt cancer cell metabolism, offering a potential avenue for therapeutic intervention across various cancer types." (PMID 40243996, 2025). "Glycolytic enzymes such as LDHA, PKM2, HK2, and ENO1, along with nutrient transporters like GLUT1, ASCT2, and LAT1, are consistently upregulated across multiple cancer types and have been linked to poor prognosis and therapy resistance." (PMID 41154605, 2025). "Many cancer cells overexpress hexokinase 2 (HK2), which catalyzes the first step of glycolysis by phosphorylating glucose and trapping it in the cell." (PMID 40573210, 2025). "HK-2, a key glycolytic enzyme, also plays a regulatory role in the pyroptosis of cancer cells induced by tretinoin (TPL)." (PMID 40165895, 2025). "LOXL1 antisense RNA 1 (LOXL1-AS1) enhances the cancer progression of CRC by regulating the miR-1224-5p/miR-761/hexokinase 2 (HK2) axis." (PMID 41331125, 2025). "By performing as a tumor suppressor, the miR-603 focuses on HK2 to influence cellular metabolism and prevent cancer." (PMID 40868085, 2025). "In cancer cells, HK2 is often overexpressed, driving the Warburg effect by promoting elevated glycolytic flux and lactate production even under aerobic conditions." (PMID 40433363, 2025). "Hexokinase 2 (HK2) is overexpressed in most human cancers and, as a glycolytic enzyme, significantly impacts cancer metabolism." (PMID 40076506, 2025). "HK2 is involved in calcium stabilization, and it is conceivable that HK2 can maintain the health of cancer cells and fight cell death." (PMID 39991762, 2025).